CD163 (CD163 molecule)
Diseases named in the same sentence as CD163 in open-access papers (continued):
Sharing a sentence is not in itself a finding about the gene and the disease.
tumor (continued). "The VEGF and MMPs have been identified as crucial indicators of skin cancer progression, with high concentrations of POSTN and CD163+ TAMs in the tumor stroma of skin malignancies leading to increased production of MMP1 and MMP12 in skin lesions." (PMID 37525217, 2023). "The spatial quantification of the immune cells using the GeoMx DSP technique revealed the significantly higher quantification of CD14 and CD163 in tumor regions of BM-LUAD as compared to BCBM." (PMID 37061716, 2023). "Of note, depletion of CD163+ TAMs resulted in tumor regression in a mouse model of anti-PD-1-resistant melanoma." (PMID 38033495, 2023). "YUMMER1.7 tumor tissue was collected at endpoint and used for immunohistochemical staining to analyze CD3, CD8, CD68 and CD163 positive cells in the tumor." (PMID 37964379, 2023). "We subsequently evaluated if there is a correlation between spatial distribution of CD68/CD163 subsets, T cells and tumor cells to clinical outcome parameters." (PMID 38322012, 2023). "In HER2+, the most negatively correlated proportion statistics were Tumor: H&E proportion and Stroma: H&E proportion (ρ = −0.92, P-value = 1.57e-25); Tumor: CD163 proportion and Stroma: CD163 proportion (ρ = −0.83, P-value = 4.18e-17)." (PMID 36707660, 2023). "Populations of infiltrated immune cells, such as CD163+ macrophages and CD8+ T cells, are associated with the prognosis in HCC, and immune cells in the tumor microenvironment can be a target for HCC therapy." (PMID 37724126, 2023). "We observed that MFAP5 + fibroblasts mainly infiltrated fibroblast areas that were close to M2-phenotype macrophages (marked by CD68 and CD163) but opposite to anti-tumor T cells or B cells." (PMID 37344903, 2023). "CD163+ TAMs have been found in the papillary axis, lymphoid aggregates and the tumour stroma as well as in tumour islets." (PMID 36928373, 2023). "Meanwhile, it is well known that tumor-associated macrophage (TAM, CD68+ or CD163+) infiltration in tumors is associated with poor prognosis in cancer patients." (PMID 37259060, 2023). "It has previously been reported that macrophages expressing CD163 in the tumour microenvironment can lead to a poor prognosis for cancer patients." (PMID 36745657, 2023). "To address how Q11 affects cancer cells through macrophages, we performed the immunohistochemical staining for CD68 (macrophage marker) and CD163 (M2 marker) on tumor tissue slices." (PMID 37875398, 2023). "A study on OS demonstrated that CD163-positive M2 macrophages play a role in inhibiting tumor progression." (PMID 37031292, 2023). "Gene Set Enrichment Analysis revealed that A2M promoted tumor development through enhancing immune cell related signal pathways, while CD163 and FPR1 inhibited tumor development through activated carcinogenic signal pathways." (PMID 38115318, 2023). "The other GBMs from I:1 and II:4 also showed a significant infiltration of CD8+ T cells and CD163+ macrophages in the tumor immune microenvironment." (PMID 37529690, 2023). "Immunosuppressive cells and tumor cells both gathered at a relatively short distance, and CD68+ CD163+ macrophages (tumor-promoting M2 macrophages) were diffusely distributed within tumor cores and located close to tumor cells after PD-L1 blockade." (PMID 37488287, 2023). "The mean values of CD163+ M2-macrophages in the tumor center were 7.65 and 30.07 in the invasion front." (PMID 36836239, 2023). "The overexpression of POU1F1 in cancer cells increases CXCL12 chemokine secretion, which promotes monocyte recruitment to the tumor microenvironment and macrophage transformation into CD163+ macrophages." (PMID 36373483, 2023). "Multiplex immunohistochemistry (mIHC), performed in-situ on the same tissue samples as the single-cell expression, confirmed a higher infiltration of CD68+ macrophages and of CD68+ CD163+ M2-MΦ in tumor tissues compared to their matched adj-normal tissues." (PMID 36750562, 2023).
tumor (continued). "We found that the number of infiltrating CD163+ macrophages in the tumor stroma of patients with PIS was significantly higher than that in the PS group." (PMID 36373483, 2023). "Clustering of the tumor microenvironment imaging data revealed a CD163+XCR1+ cell subset that was enriched in the stroma region." (PMID 37731497, 2023). "The data showed that SIGLEC15, CD68 and CD163 gene expression was broadly upregulated in tumor tissues compared with normal tissues." (PMID 37234161, 2023). "During PDAC progression, the number of macrophages increases with the stage of disease and a higher tumor infiltration by CD163+ macrophages correlates with shorter 5-year overall and recurrence-free survival." (PMID 37449210, 2023). "Tumor-associated macrophages (TAMs) were identified by CD68, CD14, CD163 and HLA-DRA and cancer-associated fibroblasts (CAFs) were characterized by COL1A1, COL3A1, MMP2, and SPARC." (PMID 37007745, 2023). "Studies showed that the frequency of tumor-promoting M2 macrophages (CD163+ CD206+) in the bone marrow of AML patients is elevated compared to healthy donors which decreases patient survival." (PMID 37809073, 2023). "In contrast, specific depletion of CD163 macrophages results in tumor regression and massive infiltration of activated T cells, including both CD4+ and CD8+ cells." (PMID 37176042, 2023). "Among 22 GC patients who received immunotherapy at PUMCH, patients with high expression of CD68 and CD163 in tumour tissues had a lower ORR." (PMID 37199594, 2023). "Upon in vivo anti-PD-L1 antibody administration, TMZ-resistant GBM tumor tissues showed abundant infiltration of CD163+ M2 macrophages." (PMID 37731483, 2023). "MIF assays were performed to examine immunological marker expression levels, including CD8, CD68, CD163, PD-L1, and PD-1, in the tumor, stroma, and total region." (PMID 38023213, 2023). "Positive immune cells were observed in all areas but in different proportion for certain types of cells as for example CD209+ immature DC and CD163+ M2-type MΦ were more abundant at the tumor margin." (PMID 37435060, 2023). "The cell density of CD68/CD163 subsets varied between 0.2 and 0.7% (tumor nests and squamous epithelium, respectively) and 0.2 - 6.8% (stroma)." (PMID 38322012, 2023). "In parallel, we found a positive relationship with CD163 M2-like macrophages suggesting the contribution of immune activation when tumours have higher S100A2 expression." (PMID 37476187, 2023). "These immeNPs are camouflaged with cancer cell membranes for tumor homing and opsonized with anti‐CD163 antibodies for specific MP recognition and uptake." (PMID 37867225, 2023). "With our approach, IHC-stained information including PD-L1, CD8+T cells, and CD163+ macrophages were co-registered into H&E-stained tumor immune micro-environment, generated a combined feature set to predict the NAC response." (PMID 36707660, 2023). "Given that CD163+ cells have been shown to reduce T-cell abundance, a double labeling procedure using CD163 (brown) and the anti-tumor effector T cell marker CD8 (red), was carried out on the entire patient cohort." (PMID 37373066, 2023). "Immunofluorescence images using CD163 staining showed that M2 macrophages accumulated at the tumor border." (PMID 37441589, 2023). "The results show that the prodrug nanoparticles have regular morphology and stable structure, especially mAb-CD163-PDNPs, which can actively target TAMs at tumor sites, respond to the acidic environment in tumor cells, and release drugs." (PMID 37111726, 2023). "The presence of TREM2+CD163+ macrophages suggests an immunosuppressive and tumor promoting phenotype of CRCpMMR TAMs, as previously reported." (PMID 37370706, 2023). "While depleting TAMs, mAb-CD163-PDNPs can actively enrich drugs at the tumor site and have a strong inhibitory effect on TAMs and tumor cells." (PMID 37111726, 2023). "In contrast, Stroma: CD8 proportion and Tumor: CD163 purity were positively correlated with RCB significantly." (PMID 36707660, 2023).
tumor (continued). "MISTRG mice support the development of human bone marrow mononuclear cells, NK cells and CD163+ tumor infiltrating macrophages." (PMID 37646021, 2023). "M2 macrophages, which express CD163, are the predominant phenotype of TAMs and contribute significantly to tumor malignancy by promoting cell proliferation, invasion, angiogenesis, immunosuppression, and metastasis." (PMID 36980788, 2023). "The immeNPs utilized cancer cell membrane (CCM) camouflage for tumor homing and antibody‐receptor interaction for specific anchoring to the CD163 marker on the surfaces of M2‐TAMs and DCs." (PMID 37867225, 2023). "The BLR and SLR were significantly associated with the densities of CD163 cell infiltration and CD8 cell infiltration in the tumor tissue, respectively (p = 0.032 for BLR and p = 0.016 for SLR)." (PMID 36983926, 2023). "The CD68+ and CD163+ cells were more abundant in the tumor than DCs and found both in the tumor epithelium and in the tumor stroma around the neoplastic glands." (PMID 37435060, 2023). "HFD significantly increased the numbers of monocyte-derived IBA1+, CD163+, and CD11c+ cells (P < 0.0001, P < 0.0001, P = 0.0005) in the contralateral, non-tumor-bearing mammary gland." (PMID 37801190, 2023). "In both tumors from this patient, over 80% of the cells in the tumor were myeloid cells, and the myeloid compartment shifted from high expression of CD163 to intermediate expression of CD14 and CD204 at resistance." (PMID 37620318, 2023). "Higher CD209+/CD83+ cell density ratio at the tumor margin was associated with higher risk of ADT and lethal PCa while higher density of CD163+ cells in the normal-like adjacent epithelium was associated with a higher risk of lethal PCa." (PMID 37435060, 2023). "To observe the effect of HK010 on TAMs, we detected the expression of CD68 and CD163 in tumor tissues." (PMID 37259060, 2023). "Both samples from the primary tumor and recurrence contained high numbers of CD163+ cells, especially in the tumor margins compared to the center of the tumor." (PMID 36776000, 2023). "The expression of CD163 was significantly increased in the tumor tissue of the hypoxia‐induced group, suggesting increased infiltration of M2‐type macrophages." (PMID 37081748, 2023). "C3aR was observed in tumor-associated macrophages (TAM) expressing CD68, CD18, CD163, and the proangiogenic VEGF." (PMID 37174113, 2023). "Clusters 1, 5, 11, and 17 all appeared to express significant amounts of CD163 (except cluster 11) and MSR1 (encodes CD204) and variable MRC1 (encodes CD206), classic markers of immunosuppressive/tissue reparative/tumor promoting M2 macrophages." (PMID 36966348, 2023). "Spatial distances of CD4+ T cells–CD38+ T cells, CD4+ T cells–neutrophils and CD38+ T cells–neutrophils prolonged and they were replaced by CD163+ macrophages in PT along with tumour progression." (PMID 37491740, 2023). "The final results also show that the mAb-CD163-PDNPs have achieved the highest tumor suppression rate (81%) and the best therapeutic effect, and it also plays a positive role in regulating the immune microenvironment." (PMID 37111726, 2023). "OESO_0120 had low intra-tumoural CD8+ cells in both pre- and post-tumour tissues, along with low intra-tumoural CD163+ and FoxP3+ cells in pre- tumour tissue, consistent with a likely immune desert phenotype." (PMID 37965317, 2023). "High tumour core CD8+ T cell infiltration, and a low tumour margin infiltration of CD163+ cells was also associated with improved survival." (PMID 37965317, 2023). "We observed that CD14+, CD68+, and CD163+ monocytes and CK+ tumor cells predominantly expressed LAIR-1 more than other cell types." (PMID 36960400, 2023). "The results of our analysis revealed that only the BLR and SLR were significantly associated with CD163 macrophage and CD8 T cell infiltration in the tumor tissue, respectively." (PMID 36983926, 2023).
tumor (continued). "Taken together, strong coexpression of PSGL-1 and CD163 in the tumor identifies PSGL-1 as a possible checkpoint on suppressive TAMs." (PMID 37819238, 2023). "In particular, MHCII+ CD163− TAMs were the earliest tumor-infiltrating immune population during the regression process that doubled between R0 and R1 lesions and significantly increased at R2 stage." (PMID 37526660, 2023). "We found that CD163 was elevated in CRC tumor tissues (p = 0.0002) and positively correlated with a worse pathological stage." (PMID 38136340, 2023). "The cell density of CD45+ leukocytes and CD68/CD163 subsets was generally higher in the stroma than in tumor nests (HNSCC) or squamous epithelium (controls)." (PMID 38322012, 2023). "According to the current literature, M2 (CD163+) polarized TAM has been described as an inducer of tumor migration and invasion in SGCs." (PMID 37465638, 2023). "It is important to emphasize in this context, that beside T cells, also the CD68/CD163 subsets and tumor cells expressed PD-1 to some extent." (PMID 38322012, 2023). "The abundance of CD3(+) and CD8(+) infiltrating lymphocyte and macrophages (CD163(+)) in tumor tissues were significantly decreased in A20-overexpressing tumor tissues." (PMID 37607946, 2023). "As a haemoglobin scavenger receptor, the overexpression of CD163 was observed to be significantly correlated with tumour progression and poor prognosis in multiple human cancers, which is consistent with our results." (PMID 36826154, 2023). "Our studies of MDMs suggest that some of these are M1-polarized MΦ, but based on CD68, CD80, CD163, and CD206, which are typically used for MΦ polarization, it is apparent that tumor-associated MΦ subsets occupy a broad spectrum within this classification." (PMID 38322012, 2023). "Within all CD68/CD163 subsets as well as of the CD45+ leukocytes the MND to next tumor cells or keratinocytes was significantly lower in the HNSCC groups compared to the controls." (PMID 38322012, 2023). "In their study, CD8 T cells and CD163- macrophages were more closely located near tumor cells after NAT." (PMID 37587309, 2023). "To assess the association of Siglec-15 expression with tumor-infiltrating macrophages, we analyzed the gene expression levels of Siglec-15 and tumor-infiltrating macrophage markers (CD68 and CD163) in 31 types of tumor tissues from the TCGA and GTEx databases." (PMID 37234161, 2023). "In our study, we calculated the positive cell density for all biomarkers of immune cells (CD3, CD4, CD8, CD19, and CD163) in both the tumor region and IM." (PMID 37090736, 2023). "The present study shows that the spatial distribution of CD4+, CD8+, CD68+, and CD163+ immune cells differs between the tumor center and invasion front of OSCC." (PMID 36836239, 2023). "T-lymphocytes (CD3, CD4, CD8) and macrophages (CD68, CD163) were also present in tumour cell areas (iTILs) (B + D)." (PMID 36726072, 2023). "Herein, we evaluated if the expression of E-cadherin, STAT3, NF-κB, CD163, PD-L1, and CXC12 would be associated with a poor prognosis for patients with tumours with low (1/2) and high (3/4) modified Dukes’ classification in primary CRC." (PMID 36857852, 2023). "Considering this different expression and relative spatial distribution we decided to deeply score this CD163+ macrophage population, potentially resembling pro-tumor FL myeloid cells." (PMID 37373066, 2023). "CD163+ TAMs recognised as M2 have been found in the tumour stroma and tumour islets, mainly distributed around the microvasculature or between tumour cells." (PMID 36928373, 2023). "Next, we determined what proportion of PD-1-expressing T cells had contact with PD-L1-expressing CD68/CD163 subsets and tumor cells." (PMID 38322012, 2023). "Two patients with partial response had higher SIA, derived from cell counts considering complement co-expression by CD68+CD163+ macrophages, in comparison to one patient with tumour progression." (PMID 36724681, 2023).
tumor (continued). "High levels of CD163 TAMs and tumor infiltrating lymphocyte (TIL) subsets were also related to blood vessel invasion (CD31 positive)." (PMID 36598153, 2023). "The first is the so-called TAM1, which exhibits a pro-inflammatory phenotype and is thought to inhibit tumor development and extension; the second is TAM2, which expresses the marker CD163 and supports tumor growth and progression." (PMID 37086293, 2023). "In the gem-RT group, less CD8 T cells and a higher CD163+ macrophages to CD8 ratio were noted in the tumor tissue, suggesting a more immune suppressive profile in the tumor tissue." (PMID 37587309, 2023). "In the myeloid compartment, there were more CD163− macrophages in the tumor tissue of upfront surgery and neoadjuvant FOLFIRINOX group." (PMID 37587309, 2023). "The mean nearest distance (MND) between CD68/CD163 subsets and T cells to tumor cells in HNSCC or keratinocytes in control tissue was determined as another distance and density correlate." (PMID 38322012, 2023). "The tumor margins showed the highest infiltration, in particular with CD163+ cells which accumulated more at the frontier between the tumor and the stroma." (PMID 37435060, 2023). "CD68 was found predominantly in and around pan-cytokeratin positive (CK+) tumor nests, whereas CD163 was expressed more consistently, throughout the tumor stroma." (PMID 38322012, 2023). "More importantly, immunohistochemical (IHC) staining showed that the overexpression of IL1α significantly increased the infiltration of CD163+ or CD204+ macrophages into the xenografted tumor tissues by 4.8‐ and 5.1‐fold, respectively." (PMID 37551997, 2023). "In the mice bearing orthotopic 4T1 TNBC, we observed that the tumor‐infiltrating TAMs and DCs prominently upregulated their CD163 expression compared to other cells in the tumor tissue." (PMID 37867225, 2023). "Several markers such as MHCII, CD80, and iNOS have been identified as M1 subtype TAM that can prevent tumor progression, while other markers including CD163, IL‐10, and Arg1 are regarded as M2 subtype TAM that can promote GBM progression." (PMID 37309294, 2023). "The CD68+, CD68+CD163+, and CD68+CD163+CD206– macrophages were abundant in both tumor and stroma regions." (PMID 37723144, 2023). "The most abundant non‐neoplastic cells are a population of CD163+ M2‐like TAMs, which support tumor proliferation, regulate immunosuppression, and contribute to cerebral edema." (PMID 36300592, 2023). "Different subgroups of background ICs, including tumour-associated macrophages (TAMs), were assessed and scored for CD4, CD8, FOXP3, and CD163 expression." (PMID 38175373, 2023). "In order to explore functional lncRNAs during the development of pro-carcinogenic macrophages, CD163+ cells and CD11b+ cells were isolated from tumor tissues and paracancerous tissues of three PDAC patients and labeled as TAMs and NTRMs, respectively." (PMID 38098044, 2023). "Consistent with a clinical trial of CRC patients, metformin treatment significantly decreased the rate of M2 macrophages in the tumor defined by CD163+/ CD68+ expression." (PMID 37686159, 2023). "Flow cytometry analysis of dissociated MØs from 231 TFM spheroids and co-cultures of MDA-MB-231 tumor cell and macrophage aggregates (231 TM) confirmed higher expression of the M2 surface marker CD163 compared to control M0 MØs." (PMID 38076998, 2023). "The results show that NK, B cell, and CD8+ T cell infiltration was significantly increased in tumours with low CD163 expression." (PMID 36826154, 2023). "In TNBC, the most negatively correlated proportion statistics were Tumor: H&E proportion and Stroma: H&E proportion (ρ = −0.95, P-value = 3.01e-33); and Tumor: CD163 proportion and Stroma: CD163 proportion (ρ = −0.88, P-value = 2.52e-21)." (PMID 36707660, 2023). "It is therefore possible that, in PDAC, a high level of CD163+ TAMs exert immunosuppressive activity by inducing CTLA4 expression in tumor-infiltrated T cells." (PMID 35418199, 2022).